EGFR (epidermal growth factor receptor)
Diseases named in the same sentence as EGFR in open-access papers (continued):
Sharing a sentence is not in itself a finding about the gene and the disease.
tumor (continued). "Although almost all of the patients in our study showed an overexpression of EGFR on their tumour tissues, none of the samples in our cohort revealed any of these favourable mutations." (PMID 30634942, 2019). "Because only two cases with ALK-positive tumours were identified in the EGFR/KRAS wild-type group, these data were not statistically analysed." (PMID 30953094, 2019). "The MGG70R-GSC line established from MGG70R formed xenografts retaining EGFR amplification and EGFR overexpression, while MGG70RR-GSC established from MGG70RR generated tumours that lacked EGFR amplification and EGFR overexpression." (PMID 30644426, 2019). "Triple-negative breast tumor cells express basal markers, such as epidermal growth factor receptor (EGFR) and cytokeratin 5/6 at high levels." (PMID 30987191, 2019). "miR-1296-5p acts as a tumor suppressor, at least partly, by targeting CDK6 and EGFR." (PMID 30530570, 2019). "In contrast, there was no phosphorylation detected in EGFR, suggesting that it was not involved in the signaling of this tumor." (PMID 30499260, 2019). "The results of our research may partially explain the different PD-L1 status in EGFR-TKI sensitive and resistant tumours and unveil the regulatory mechanisms of PD-L1 in EGFR-TKI resistant NSCLC." (PMID 31747941, 2019). "IHC performed on SCR shRNA xenografts showed the tumour cells to be negative for the expression of the IDH1R132H‐mutated protein product with strong nuclear ATRX expression and GFAP and EGFR immunopositivity." (PMID 30565681, 2019). "These signaling pathways have been reported to be co-activated or have cross-talked with EGFR in HCC and other tumor types, and could consequently promote tumorigenesis." (PMID 31515263, 2019). "Furthermore, our findings showed that miR-411-5p/3p promoted lung tumor growth in vivo, decreased SPRY4 expression dramatically, and induced EGFR, AKT signaling activation, as well as epithelial–mesenchymal transition (EMT) simultaneously in tumor tissues." (PMID 30390072, 2019). "Curiously, conventional effector T cells do not express EGFR and thus, they do not benefit from the presence of EGFR ligands in the tumor microenvironment." (PMID 31921216, 2019). "On the other hand, EGFR inhibition did not influence the levels of PD-L1, which reached the same concentration as in the control tumor." (PMID 31480495, 2019). "Targeted agents directed against EGFR, such as cetuximab and panitumumab, and those directed against VEGF, such as bevacizumab, have been shown to facilitate a more immunogenic tumor profile in preclinical models and, as such, are reasonable potential adjuncts to ICIs in MSS CRC." (PMID 30654522, 2019). "Since EGFR and TGF‐β signaling pathways involved in cell movement and metastasis were found to be altered in gene expression analysis, we explored the potential for TAE226 to inhibit tumor invasion and metastasis of EWS cells." (PMID 31692287, 2019). "His GBM tumor tissue demonstrated O6-methylguanine-DNA methyltransferase (MGMT) promoter methylation, wild-type isocitrate dehydrogenase 1/2 (IDH1/2) and amplification of the epidermal growth factor receptor (EGFR) gene." (PMID 30766509, 2019). "Hetero-dimerization of EGFR with HER2, HER3 or HER4 might limit anti-tumor effect of EGFR inhibition, and pan-HER inhibitor could improve the efficacy of EGFR inhibition through limiting receptor cross-talk signaling." (PMID 30658422, 2019). "One somatic EGFR mutation, D522Y, was also identified in the EGFR extracellular domain of an intrinsic-resistant tumour; however, residue 522 is not in the EGFR cetuximab-binding domain." (PMID 31653970, 2019). "Validation with RNA-seq data of blood platelets shows that DDR achieves the superior performance in classification of six different tumor types as well as molecular target statuses (such as MET or HER2-positive, and mutant KRAS, EGFR or PIK3CA) with smaller sets of biomarkers." (PMID 31752658, 2019).
tumor (continued). "The development of molecularly targeted therapies, as well as ICIs, has improved outcomes in the metastatic setting for NSCLC patients who harbor somatically activated oncogenes such as EGFR and BRAFV600, rearranged ALK or ROS1, or PD-L1 expression ≥50% of tumor cells." (PMID 30818873, 2019). "For this reason, the analyses for concordance, sensitivity and specificity compared to primary tumor tissue are not useful in the post-EGFR cohort of patients." (PMID 31597339, 2019). "PARK2 exerts a tumor suppressive function in vitro and in vivo, including retarding growth, migration, invasion, and metastasis and promotes apoptosis of NSCLC cells through inhibition of the EGFR/AKT/mTOR pathway." (PMID 31508359, 2019). "HER2 expression was higher in mice who received lapatinib in CWR22 tumours (p = 0.0333), but no corresponding change in EGFR was observed." (PMID 31209328, 2019). "EGFR is widely expressed in normal, non-neoplastic tissues, and its use as a target antigen can lead to severe on-target, off-tumor immunotoxicity." (PMID 31417564, 2019). "Here, ADAM-mediated shedding of membrane bound substrates, such as growth factors, cytokines and adhesion molecules is thought to promote tumor growth and/or progression, best demonstrated by the role of ADAM17 in epidermal growth factor receptor (EGFR) signaling." (PMID 31013576, 2019). "In our study, the positive rates of EGFR were 63.6 and 58.3% in primary tumours of patients with ovarian and non-ovarian metastases, respectively, which was in line with previous studies." (PMID 30858756, 2019). "Earlier studies showed that SW620 and HT29 are resistant to EGFR inhibition (cetuximab), which corresponds to the lack of activity of erlotinib on tumor growth, as well as on the metabolic activity and apoptosis demonstrated here." (PMID 31783534, 2019). "In this series, only one patient had a fusion detected in pretreatment tumor tissue and subsequently had anti-EGFR therapy but did not have a clinical response." (PMID 33015522, 2019). "In this study we investigated the detection of metabolites of hyperpolarized [1-13C]pyruvate with regard to monitoring treatment response using 213Bi-anti-EGFR-MAb (the alpha-emitter 213Bi coupled to an anti-EGFR antibody) in an in vitro system using LN18 and EJ28Luc tumor cells." (PMID 31165773, 2019). "Epidermal growth factor receptor (EGFR) is highly expressed in OC, as well as in other tumor cells." (PMID 31652539, 2019). "Activated canine non-B, non-T NK cells (CD3−CD21−CD5−TCRαβ−TCRγδ−) for 13~17 days ex vivo showed ADCC ability against trastuzumab- or cetuximab-coated target tumor cells expressing various levels of human epidermal growth factor receptor 2 (HER-2) and epidermal growth factor receptor (EGFR)." (PMID 31610784, 2019). "Our data support the idea that simultaneous targeting of EGFR and MET could be a promising therapeutic strategy inhibiting not only tumor cell growth but also its metastasis." (PMID 31649529, 2019). "However, in the EGFR‐low‐expression model (PA3029), the maximum inhibitory rate by DTLL was only up to 29.44% on Day 39, showing a smaller trend in tumor volume than vehicle group." (PMID 30681288, 2019). "No EGFR mutations were detected in cfDNA from plasma taken from the 35 NSCLC patients with EGFR wild-type tumours, regardless of the clinical stage of the disease." (PMID 30953094, 2019). "And high expression of eIF3E and eIF3J was observed more in patients with residual tumours (13/4 vs. 172/170, p = 0.0456) and without mutations in KRAS/EGFR/ALK (47/48 vs. 86/46, p = 0.0206), respectively." (PMID 31885740, 2019). "In addition to EGFR, ALK-rearrangement testing is also routine and there are a number of targeted therapies for tumours harbouring the EML4-ALK fusion gene." (PMID 30470932, 2019). "The expression of these cytokines correlated with the lack of response to EGFR targeting in patient-derived tumor xenografts." (PMID 31370270, 2019).
tumor (continued). "Specifically, patients diagnosed with left-sided tumors have appeared to have better responses with anti-EGFR therapy than with anti-VEGF therapy, with the bulk of tumor location subgroup analysis evidence coming from the available cetuximab-based phase 3 trials." (PMID 31616627, 2019). "To determine whether the regression in tumor growth by GZ17-6.02 is due to inhibition of proliferation, apoptotic cell death or both, we first determined the expression of phosphorylation of EGFR and AKT." (PMID 30899425, 2019). "Other studies also demonstrated that low-affinity CAR-T cells targeting EGFR or CD123 could distinguish malignant from normal cells and reduce the “off-tumor on-target” toxicity." (PMID 31429760, 2019). "EGFR/PYGO2 overexpression had significant correlations with surgical stage and tumor grade." (PMID 31470870, 2019). "Unlike the oncogenic addiction of EGFR-mutant NSCLC, EGFR, as one of many pathways that contributes to tumor growth in CRC, leads to certain clinical implications." (PMID 30700700, 2019). "In one case we found that EGFR-transcript levels from frozen tumour tissue did not match with protein levels in FFPE blocks." (PMID 31747973, 2019). "Furthermore, this platform allowed for tumor detection through MRI and FMI imaging compared to the untargeted formulation demonstrating how EGFR active targeting can substantially improve NPs tumor tropism." (PMID 31662751, 2019). "To determine what drives elevated EGFR levels in hypoxic tumors, we incubated three different tumor cell lines plus one endothelial cell line in hypoxia or normoxia and measured transcription by RT-qPCR." (PMID 31717697, 2019). "Additional tumor material is required for interrogating predictive biomarkers, using IHC (e.g., ALK, ROS1, PD-L1), in situ hybridization (ISH; e.g., ALK, ROS1) or sequencing techniques (e.g., EGFR, BRAF V600E, etc.)." (PMID 30818873, 2019). "A common reason is that in populations with EGFR, BRAF, MET, ALK and other gene mutations, it is not easy to produce new antigens of tumours, and the tumour mutation load is lower." (PMID 30862891, 2019). "However, EGFR inhibition initiated a rapid resistance mechanism involving non-EGFR ERBB family members, which triggered a tumor escape mechanism." (PMID 31612108, 2019). "Due to the limited patient numbers, resectability data are not available to evaluate the predictive role of the anti-EGFR mAb based on tumor location." (PMID 30296945, 2018). "Our in vitro studies showing enhanced ERK1/2 and AKT phosphorylation are corroborated by immunohistochemical data in tumor sections from GBM patients, also showing markedly stronger signals for HDAC6, EGFR, phosphorylated ERK1/2, and phosphorylated AKT compared to normal brain tissue." (PMID 30302275, 2018). "Moreover, it is conceivable that anti-EGFR and/or anti-HerB2 huAb can affect MSC-tumor cell cross-talk due to the signal delivered upon huAb/receptor interaction." (PMID 29515580, 2018). "Following this, we characterised the molecular phenotype of these tumours by examining the fluorescent intensity of several EMT, stem-like, and resistance markers, namely Snail, EGFR, cell-surface vimentin (CSV), ALDH1A and ATP-binding cassette sub-family B member 5 (ABCB5)." (PMID 29311580, 2018). "L1196M was detected in a rebiopsied tumor tissue sample from case 1 who showed resistance to both crizotinib and alectinib and significantly prolonged PFS in response to ceritinib, along with immunopositivity for EGFR and EMT markers." (PMID 29844868, 2018). "In our study neither EGF nor EGFR expression did differentiate metastasis from primary tumour, which suggests there is other mode of MMP activation." (PMID 30231850, 2018). "According to a clonal selection model, EGFR-TKI treatment may lead to the selection of T790M mutant cells, and thus even a small fraction of T790M positive tumor cells at the beginning of treatment could lead to clinical EGFR-TKI resistance." (PMID 29323170, 2018).
tumor (continued). "Other studies suggested that EGFR inhibition has no significant influence on cell proliferation, but enhances the anti‐tumor effects of starvation or chemotherapy‐induced cell stress in vitro." (PMID 30361264, 2018). "Dual inhibition of EGFR and AURKA could offer synergistic mechanisms to overcome resistance and suppress tumours such as SCCHN and NSCLC where redundancy in EGFR and AURKA signaling is observed." (PMID 29115879, 2018). "Neither EGFR expression nor phosphorylation was correlated with tumor differentiation or stage of disease." (PMID 29989001, 2018). "The distribution of EGFR and HER2 gene amplifications was studied in the intestinal-type tumours." (PMID 29046940, 2018). "We used an unbiased computational approach called Expression2Kinases (X2K) to identify the kinases that might be driving the hyperactivation of the EGFR and TGF-β pathways in QM-PDAC tumours." (PMID 30018740, 2018). "Treatment with the EGFR inhibitor erlotinib also led to decreased PD-L1 expression in tumor cell lines that harbor mutant EGFR but not in cells that have wild-type EGFR, further supporting the link between activated EGFR signaling and PD-L1 expression." (PMID 30420856, 2018). "It has been demonstrated that suppression of autophagy in epidermal growth factor receptor- (EGFR-) driven nonsmall cell lung adenocarcinoma xenografts promotes cell proliferation, tumor growth, and dedifferentiation, as well as resistance to EGFR tyrosine kinase inhibitor therapy." (PMID 30363988, 2018). "When compared to EGFR and PTEN loss in GBM tumor samples, which again were used as positive and negative controls, the 15.4% frequency of ERBB4 copy number loss behaves qualitatively similarly to that of GBM tumor suppressor PTEN." (PMID 29342193, 2018). "Our study results suggest that miRNA-874 is a negative regulator of the DOR that can suppress tumor proliferation and metastasis in HCC by targeting the DOR/EGFR/ERK pathway, which may be a potential target for HCC treatment." (PMID 29374140, 2018). "Preclinical data suggest that oncogene (EGFR and KRAS) events regulate tumor procoagulant activity." (PMID 29743116, 2018). "In the clinical practice, Pembrolizumab is already approved by FDA for first-line treatment of patients with metastatic NSCLC who shows ≥50% PD-L1-positive TCs, with no EGFR or ALK genomic tumor aberrations." (PMID 29467945, 2018). "Injection of the same quantity of this EGFR-targeted MNT alone or 111In alone at the same dose did not lead to a noticeable change in tumor growth rate." (PMID 30510514, 2018). "From these results, we found that miR-133b level was negatively correlated with EGFR and ITGB4 levels in tumor tissues, which may participate in the metastasis of ESCC." (PMID 30479571, 2018). "Free Gef or Gef-NPs alone did not observably inhibit the growth of PC-9-GR tumor xenografts that had acquired EGFR-TKI resistance." (PMID 29942660, 2018). "In vivo, CFF‐1‐treated group exhibited a significant decrease in tumor volume compared with the negative control group in subcutaneous xenograft tumor in nude mice via inhibiting EGFR‐related signal pathways." (PMID 29533017, 2018). "In this retrospective analysis of samples of the OSAG 101-BSA-05 trial, we investigated histological subgroups based on necrosis and hypoxia as markers for a nutrient-deprived tumor microenvironment as well as for phosphorylation of PRAS40 and RPS6 as downstream markers of EGFR signaling." (PMID 30129426, 2018). "To understand how RENCA macrobead-secreted tumor-inhibitory proteins regulate MEF2 expression, we explored the activity of cell-surface receptors, specifically TGF-β/SMAD, BMP and EGFR, as they have previously been shown to converge on MEF2 transcriptional regulation." (PMID 30514247, 2018). "Target-directing components such as EGFR peptide were not included in their vector; nevertheless, selective accumulation of the DNA complex in the tumor was observed." (PMID 29970866, 2018).
tumor (continued). "EGFR and IGFR are expressed on tumor cells and contribute to tumor progression." (PMID 30050899, 2018). "EGFR activates several downstream pathways, including Ras/Raf/MAPK/ERK, PI3K/Akt, STAT, and the PLC-γ signaling pathways to potentiate growth and survival of tumor cells and CSCs." (PMID 30227608, 2018). "The FDA approved erlotinib in 2004 for second-line therapy regardless of tumor histologic type or EGFR status." (PMID 29554880, 2018). "Here, we aimed to test the hypothesis that combined inhibition of EGFR, HER2, and HER3 signalling with the tyrosine kinase inhibitor AZD8931 will control growth of all wild-type tumours." (PMID 29254887, 2018). "In the OAC, but not the SCC, the cMet expression correlated with EGFR, pSTAT3 expression, and lymphovascular invasion of tumour cells." (PMID 29890775, 2018). "All other factors analyzed including age, sex, race, site of primary tumor, ECOG performance status, Child-Pugh Score, MELD score, EGFR Inhibitor Treatment (in the pre- or post-Y90 timeframe), pre-Y90 CEA, tumor size (cm), and tumor volume (cc) did not predict OS in WT compared to MUT groups." (PMID 30197760, 2018). "Induction of EMT through EGF/EGFR/ERK1/2 entailed functional consequences, as cells were equipped with enhanced migration capacity and might thereby impact local and distant tumor cell dissemination." (PMID 30261040, 2018). "In tumor tissue, the HIF-1α mRNA level correlated with the EGFR protein level (correlation coefficient: +0.36; p = 0.001), in addition, the EGFR mRNA correlated with EGFR protein level (correlation coefficient: +0.53; p < 0.001)." (PMID 30513863, 2018). "Moreover, because EGFR expression is reported to increase in tumor cells undergoing EMT10, EGFR seems attractive as a target for CTC capture and to contribute to CTC detection." (PMID 30104638, 2018). "Mutations in putative drug targets (EGFR, PDGFRA, ERBB2, and PI3K) are not always stable between primary and recurrence tumors, supporting tumor evolution during progression." (PMID 30279357, 2018). "Also, the CXCL12-CXCR4 axis promotes intraosseous tumor growth by transactivation of growth factor receptors like HER2 (NP_001005862) and EGFR (NP_001333826) in lipid rafts of PCa cells." (PMID 29396484, 2018). "To improve anti-tumor efficacy without exacerbating toxicity to normal tissue, we aimed to develop a low affinity anti-EGFR ADC." (PMID 30323890, 2018). "We proposed that the unresponsiveness of B lymphoma cells to the pro-tumor effect of HIV-positive T-cell exosomes was due to the lack of EGFR in the cells." (PMID 30389917, 2018). "However, retrospective studies showed that NSCLCs harboring EGFR mutations were associated with low response rates to PD-1/PD-L1 inhibitors, which may have resulted from low rates of concurrent PD-L1 expression and CD8(+) TILs within the tumor microenvironment." (PMID 29455650, 2018). "Subsequently, pembrolizumab, another anti-PD-1 antibody, was approved as a second-line for NSCLC patients whose tumors exhibit >50% of PD-L1 expression and as first-line treatment in patients PD-L1 positive, with no EGFR or ALK genomic tumor aberrations." (PMID 29464099, 2018). "Interestingly, lower levels of cyclic AMP, a negative regulator of epidermal growth factor receptor (EGFR) is observed in IDC serum, thereby possibly providing survival advantage for tumours and promote further growth." (PMID 29416801, 2018). "We were able to unveil a potential role of PTPIP51 in tumor promoting signaling and therapy resistance against EGFR/Her2 targeted TKIs mediated through the non-receptor kinase c-Src and the phosphatase PTP1B." (PMID 30360441, 2018).